BRCA2 (BRCA2 DNA repair associated)
Diseases named in the same sentence as BRCA2 in open-access papers (continued):
Sharing a sentence is not in itself a finding about the gene and the disease.
breast tumors (continued). "Indeed, the size distribution of deletions and the presence of a few other types of non-clustered rearrangements in RAD51C−/−, XRCC2−/−, XRCC3−/−, BRCA2−/−, or PALB2−/− mutant cells closely resembled the predominant rearrangement signature of BRCA2-deficient breast tumors." (PMID 31727117, 2019). "In the multivariate analysis, there was no observed reduction in mortality in BRCA2 mutation carriers with ER-positive breast tumours associated with the use of tamoxifen (HR = 0.91; 95% CI 0.49–1.69, p = 0.76) or with chemotherapy (HR = 1.03; 95% CI 0.51–2.06, p = 0.94)." (PMID 30723304, 2019). "When tumors were stratified by mutation and tumor type, the means of these three scores (HRD-Mean) were significantly higher in BRCA1 and BRCA2 germline mutation-associated breast vs. nonBRCA breast tumors, and between BRCA1 germline mutation-associated and nonBRCA ovarian tumors." (PMID 28831036, 2017). "In addition, alternative splicing expression profile was also successfully used in several studies aiming to discriminate subtypes of breast tumors, and specific gene expression profiles have also been identified for BRCA1, BRCA2 and CHEK2-associated breast tumors." (PMID 29108258, 2017). "The identification of a specific BRCA2-associated phenotype suggestive of an aggressive behaviour might define a subset of MBC patients (i.e., patients with high-grade breast tumours and with young age at diagnosis) who may particularly benefit from adjuvant chemotherapy." (PMID 26857456, 2016). "No indications exist for breast tumours occurring in BRCA2 mutation carrier." (PMID 20877358, 2010). "However, we did not observe increased EZH2 expression in breast tumors from BRCA2-mutation carriers (data not shown), suggesting that the main oncogenic role of EZH2 is not linked to DNA repair." (PMID 19709408, 2009). "We induced breast tumors in Balb/c mice and tested the formulations (NP, BRCA1 + NP and BRCA2 + NP) in vivo." (PMID 36631481, 2023). "Interestingly, two BRCA2 germline mutation related breast tumors were classified as not TNBC." (PMID 32164626, 2020). "Global miRNA expression profiling using NanoString technology was performed on 43 hereditary breast tumors (15 BRCA1, 14 BRCA2, and 14 BRCAX), 23 sporadic breast tumors and 8 normal breast tissues." (PMID 32087690, 2020). "Larsen and colleagues studied 183 breast tumours (33 BRCA1, 22 BRCA2) and developed a 110-probe signature to classify BRCA1 breast tumour within the basal-like subtype with an accuracy of 83% (sensitivity: 82%, specificity 85%)." (PMID 33081408, 2020). "Breast tumors were mostly invasive ductal carcinomas (occurring in milk ducts) for both BRCA1 (80%) and BRCA2 (83%) carriers." (PMID 32481735, 2020).
breast tumors (continued). "Invasive ductal carcinoma is the most common histological breast tumor typeobserved in BRCA1 and BRCA2 carriers.Other histological subtypes, including medullary and tubular carcinoma, are alsofound in this subgroup of patients (Mavaddatet al., 2012)." (PMID 31067289, 2019). "In the present study, frozen primary breast tumor samples were collected from 70 non-BRCA1/2, 33 BRCA1, 22 BRCA2, and 128 sporadic cases." (PMID 24479546, 2014). "In contrast, the vast majority of tumors arising in BRCA2 carriers were ER+, and only very few of the BRCA1/2 positive breast tumors demonstrated HER2-amplification." (PMID 23704984, 2013). "Based on gene expression data from TCGA project, we found that ROCK2 expression was positively correlated with BRCA2 expression in breast tumor donors while there is no such correlation in normal breast tissue." (PMID 39013885, 2024). "BRCA2 defective tumors are more consistent with luminal B molecular subtype, a subtype generally only found in one-fifth of non-selected breast tumors." (PMID 35135604, 2022). "We also observed that these miRNAs achieved slightly higher AUC values in BRCAX breast tumors compared to BRCA1 and BRCA2 breast tumors, suggesting that these miRNAs have higher specificity and specificity rates for hereditary BRCAX as compared to BRCA1/2-mutated breast tumors." (PMID 32087690, 2020). "In order to explore whether miRNA expression profiling could also discriminate BRCA1, BRCA2, and BRCAX breast tumors, we performed a multiple comparison to identify a miRNA signature among HBC." (PMID 32087690, 2020). "Interestingly, ER/PR status of the first breast tumor was predictive of the ER/PR of the second cancer for both BRCA1 and BRCA2 carriers, suggesting that the second tumor arises in the same genetic and environmental background with the same pathology." (PMID 32481735, 2020). "Tumors carrying mutations in the BRCA1 and BRCA2 genes, particularly in BRCA1, have more point mutations than sporadic breast tumors, which is not explained by their larger genome size owing to copy number alterations." (PMID 31182087, 2019). "Promoter methylation analysis of TCGA data showed that BRCA1 promoter methylation status in ovarian and breast tumors correlates with BRCA1 but not BRCA2 expression levels." (PMID 28831036, 2017). "The role of BRCA1, BRCA2, PRAB, and Erα genes as an oncogene responsible for the downregulation of the incidence of cancer progression is well established in a wide variety of tumors, including breast tumors." (PMID 28761624, 2017). "Although the majority of breast tumors are sporadic and do not carry germline mutations in BRCA1 or BRCA2, it has been shown that the HR DNA repair pathway is frequently disrupted by numerous mechanisms." (PMID 27788678, 2016). "In contrast, BRCA2 breast tumours are a more heterogeneous group, being broadly similar to non-BRCA–associated breast tumours, which more closely resemble post-menopausal FBCs, although with a tendency to be of high grade and HER2−." (PMID 26857456, 2016). "Little is known about miRNA deregulation in hereditary breast tumors as no miRNA expression profiling studies have been performed in normal breast tissue of BRCA1 and BRCA2 mutation carriers." (PMID 26378051, 2015). "Strikingly enough BRCA1 vs BRCA2 tumours also showed significant differences in PPI distributions (KS test: DB12 = 22.85 > Kα = 0.05 = 1.36), reflecting considerable differences in PPI wiring between the two breast tumours." (PMID 25521701, 2014). "None of these features is, however, unique and therefore none can be used to distinguish BRCA1 and BRCA2 tumors from sporadic breast tumors." (PMID 23704984, 2013).
breast tumors (continued). "BRCA1 mutant breast tumours have been reported to express higher levels of JAG1 mRNA compared with BRCA2 mutant tumours; however, this was not significant." (PMID 23863842, 2013). "Hypermethylation of DR5 (P = 0.001), DCR1 (P = 0.00001), DCR2 (P = 0.0000000005) and BRCA2 (P = 0.007) and hypomethylation of DR4 (P = 0.011) in sporadic breast tumor tissues suggested a weak/aberrant activation of the DDR/apoptotic pathway in breast tumorigenesis." (PMID 21092294, 2010). "53BP1 expression was recently found frequently decreased in a subset of basal-like/triple-negative breast cancers and in BRCA1 or BRCA2 negative breast tumors." (PMID 21054854, 2010). "In addition, it has been demonstrated that the BRCA2 gene is negatively regulated by protein interactions with gene products of the EMSY gene which, in turn, is frequently amplified in sporadic breast tumours." (PMID 19589159, 2009). "BRCA2 promoter hypermethylation has not been found in breast tumours, although it has been reported in ovarian tumours." (PMID 16846527, 2006). "The present study does not provide conclusive evidence that BRCA2 is the sole target for deletions at 13q12-q13 in breast tumours." (PMID 8932343, 1996). "Notably, the calculated BRCA scores using the BRCA1/2-based profile achieved the best classification accuracy when comparing familial breast tumors from sporadic ones (right, AUC = 0.861 for BRCA1 vs. sporadic, ACU = 0.809 for BRCA2 vs. sporadic and AUC = 0.84 for BRCA1/2 vs. sporadic)." (PMID 29146938, 2017). "Retention of the normal BRCA1 or BRCA2 allele (absence of locus-specific loss of heterozygosity (LOH)) is observed in 7% of BRCA1 ovarian, 16% of BRCA2 ovarian, 10% of BRCA1 breast, and 46% of BRCA2 breast tumors." (PMID 28831036, 2017). "A similar analysis of breast tumors arising in carriers of BRCA1 mutation, analyzed from a different dataset (The Netherlands Cancer Institute), revealed highest resemblance in 17 of 18 cases to basal-A lines (not shown), while two BRCA2 mutation associated cases most resembled luminal cell lines." (PMID 19582160, 2009). "Our observation followed by statistical analysis of methylation status in breast tumors along with transcript expression revealed a negative correlation for TRAIL, DR4, CASP8, ATM, CHEK2, BRCA1 and BRCA2 CpG sites." (PMID 21092294, 2010). "The study group consisted of 67 primary breast tumours with and without BRCA1 or BRCA2 abnormalities." (PMID 19589159, 2009). "However, miRNAs validated by quantitative polymerase chain reaction (qPCR) (miR-4417 and miR-423-3p) could only discriminate hereditary (BRCA1, BRCA2, and BRCAX) from non-hereditary breast tumors (70.1% accuracy)." (PMID 32087690, 2020).
Hereditary breast and ovarian cancer syndrome (159 papers, 1999 to 2026). An autosomal dominant inherited syndrome caused by mutations in the BRCA1 or BRCA2 genes. "Out of five remaining carriers with diffuse GC not meeting HDGC criteria, one met Hereditary Breast and Ovarian Cancer (HBOC) syndrome testing criteria and had a BRCA2 variant." (PMID 40446793, 2025). "The large number of cases of HBOC syndrome is caused by the presence of germline mutations in either the BRCA1 or the BRCA2 gene located on chromosome 17q21 and 13q12-13, respectively." (PMID 40648909, 2025). "We previously reported the prevalence of germline variants among Japanese patients with BRCA1/BRCA2-wildtype HBOC syndrome and a strong family history." (PMID 39003386, 2024). "BRCA2 c.5286T>G (p.Tyr1762*) is a Northern Russian founder variant accounting for half of BRCA2 pathogenic alleles in hereditary breast-ovarian cancer patients from the Arkhangelsk region." (PMID 39273284, 2024). "Germline alteration of HR-related genes, such as BRCA1 and BRCA2, causes hereditary breast and ovarian cancer (HBOC)." (PMID 38589490, 2024). "It is interesting to note that the described variant represents 32% of all BRCA2 gene variants identified in subjects with suspected HBOC syndrome in the province of Rimini." (PMID 37046793, 2023). "Germline pathogenic mutations of BRCA1 and BRCA2 suppress the HR mechanism and cause hereditary breast and ovarian cancer (HBOC) syndrome." (PMID 35785170, 2022). "Pathogenic germline mutations in the BRCA1 and BRCA2 (BRCA1/2) genes contribute to hereditary breast/ovarian cancer (OC) in White/mestizo Colombian women." (PMID 35641219, 2022). "Mutations in the BRCA1 or BRCA2 genes result in the clinical presentation known as hereditary breast and ovarian cancer syndrome." (PMID 35685436, 2022). "Hereditary breast and ovarian cancer syndrome (HBOC) is a hereditary tumor that can be definitively diagnosed by the detection of a germline mutation of the BRCA1 or BRCA2 gene." (PMID 35769138, 2022). "The most common cause of hereditary BC is a GPV in BRCA1 or BRCA2 (BRCA1/2) associated with hereditary breast and ovarian cancer (HBOC)." (PMID 35806485, 2022). "PVs in BRCA1 and BRCA2 are classically associated with hereditary breast and ovarian cancer syndromes." (PMID 36232851, 2022). "The most common contributors to hereditary BC are BRCA1 and BRCA2, which are associated with hereditary breast and ovarian cancer (HBOC)." (PMID 35806485, 2022). "A study of 585 Slovak families with hereditary breast and ovarian cancer syndrome (HBOC) found evidence of pathogenic SNPs affecting the C-terminus of BRCA2 in a large-scale sequencing study." (PMID 33503928, 2021). "The pathogenic role of the germline BRCA2 c.9976A>T and c.10095delinsGAATTATATCT variants in hereditary breast and ovarian cancer (HBOC) patients was evaluated." (PMID 33672545, 2021). "The potential pathogenic role of germline BRCA2 c.9976A>T and c.10095delinsGAATTATATCT was evaluated in hereditary breast and ovarian cancer (HBOC) patients by investigating 2491 probands and verified in an independent cohort of 122,209 patients." (PMID 33672545, 2021). "BRCA1 and BRCA2 mutations in women of different ethnicities undergoing testing for hereditary breast-ovarian cancer." (PMID 35096615, 2021). "The representative genes involved in HR are BRCA1 and BRCA2, whose deleterious variants are associated with hereditary breast and ovarian cancer (HBOC) syndrome." (PMID 35008774, 2021). "An increased melanoma risk has been documented in carriers of germline mutations causing other cancer syndromes, including hereditary breast and ovarian cancer (BRCA1/BRCA2), retinoblastoma (RB1), or xeroderma pigmentosum (XPs)." (PMID 33050356, 2020).
Hereditary breast and ovarian cancer syndrome (continued). "Up to 25% of women diagnosed with HGSC have germline deleterious mutations in BRCA1 or BRCA2 characteristic of hereditary breast and ovarian cancer syndrome (HBOC), while somatic mutations have been detected in 3–7%." (PMID 33233347, 2020). "Approximately 25% of women diagnosed with tubo-ovarian high-grade serous carcinoma have germline deleterious mutations in BRCA1 or BRCA2, characteristic of hereditary breast and ovarian cancer syndrome, while somatic mutations have been detected in 3–7%." (PMID 33233347, 2020). "Germline mutations in the BRCA1 and BRCA2 genes cause hereditary breast and ovarian cancer syndrome (HBOC)." (PMID 32468491, 2020). "It is well-known that the inherited mutations of BRCA1 and BRCA2 genes resulted in hereditary breast and ovarian cancer syndrome (HBOC)." (PMID 32821249, 2020). "BRCA1- and BRCA2-associated hereditary breast and ovarian cancer syndromes are among the best-known and most extensively studied hereditary cancer syndromes." (PMID 32733558, 2020). "The risk of serous PPC increases in patients with hereditary breast and ovarian cancer syndrome or BRCA1 or BRCA2 mutations." (PMID 31823088, 2019). "Inherited pathogenic variants in BRCA1 and BRCA2 are the most common causes of hereditary breast and ovarian cancer (HBOC)." (PMID 31395037, 2019). "A relevant fraction of BRCA2 variants is associated with splicing alterations and with an increased risk of hereditary breast and ovarian cancer (HBOC)." (PMID 31191615, 2019). "Heterozygous germline mutations in BRCA1 and BRCA2 are responsible for the majority of hereditary breast and ovarian cancer (HBOC) syndrome patients." (PMID 31921645, 2019). "Hereditary breast and ovarian cancer syndrome (HBOC) is most frequently caused by mutations in BRCA1 or BRCA2 (in short, BRCA) genes." (PMID 29659587, 2018). "Although the majority of BC and OC cases are sporadic, approximately 10% of ovarian cancer cases and 3–5% of BC cases are due to germline mutations in the genes BRCA1 and BRCA2, which has been described as hereditary breast-ovarian cancer (HBOC) syndrome." (PMID 28961279, 2017). "Germline variants within BRCA1 or BRCA2 genes account for approximately 25% of familial aggregations of breast-ovarian cancer that are clinically manifested as hereditary breast and ovarian cancer syndrome (HBOC)." (PMID 29021870, 2017). "BRCA1 and BRCA2 mutations explain approximately one-fifth of the inherited susceptibility in high-risk Finnish hereditary breast and ovarian cancer (HBOC) families." (PMID 28738860, 2017). "Heterozygous BRCA1 and BRCA2 mutations underlying hereditary breast and ovarian cancers (HBOCs) have also been reported to be involved in cellular radiosensitivity and cancer susceptibility." (PMID 28729543, 2017). "Germline pathogenic variants in BRCA1 and BRCA2 (BRCA) are the main cause of Hereditary Breast and Ovarian Cancer syndrome (HBOC)." (PMID 29161300, 2017). "Germline variants within BRCA1 or BRCA2 genes account for approximately 25% of familial aggregations of breast-ovarian cancers." (PMID 29021870, 2017). "BRCA1 and BRCA2 (collectively named BRCA hereafter) are the main genes causing hereditary breast and ovarian cancer syndrome (HBOC), and are also associated with an increased risk of prostate and pancreatic cancers." (PMID 29161300, 2017). "Germline mutations in BRCA1 and BRCA2 genes (BRCA1/2) predispose to hereditary breast and ovarian cancer syndrome (HBOC), and their dysregulation increases the risk of cancers." (PMID 29383094, 2017). "Next-generation sequencing (NGS) has enabled new approaches for detection of mutations in the BRCA1 and BRCA2 genes responsible for hereditary breast and ovarian cancer (HBOC)." (PMID 27793035, 2016).